ACER3 (alkaline ceramidase 3)
Diseases named in the same sentence as ACER3 in open-access papers (continued):
Sharing a sentence is not in itself a finding about the gene and the disease.
B-cell acute lymphoblastic leukemia (1 paper, 2021). A neoplasm of lymphoblasts committed to the B-cell lineage, typically composed of small to medium-sized blast cells. "ACER3 coregulates cell proliferation and survival with ACER2 and plays an important role in leukemia development; while TCL6 is associated with clinical outcomes of B-cell acute lymphoblastic leukemia patients; TFDP2 plays core roles in apoptosis and cell proliferation." (PMID 34722498, 2021).
cholestasis (1 paper, 2025). Impairment of the bile flow caused by obstruction within the liver, or outside the liver in the bile duct system. "We found that cholestasis upregulates ACER3, while ACER3 ablation promotes the binding of CER(d18:1/18:1) to LXRβ to activate LXRβ signaling, thereby improving BA detoxification and lipogenesis to attenuate CLI." (PMID 40025008, 2025). "Importantly, no significant sex-specific differences were observed in ACER3 expression in human livers, and cholestasis-induced upregulation of ACER3 and CER(d18:1/18:1) was comparable in both sexes." (PMID 40025008, 2025). "These suggest that cholestasis may drive ACER3 upregulation through multiple regulatory pathways involving these transcription factors." (PMID 40025008, 2025). "Our study also determined whether these sex-specific effects of Acer3 ablation observed in mice applied to human cholestasis." (PMID 40025008, 2025). "Hepatic ACER3 was found to be upregulated by cholestasis and positively correlated with CLI severity in patients with cholestasis." (PMID 40025008, 2025). "Online data mining suggested that cholestasis might upregulate ACER3 via transcription factors SP1, EGR1, and STAT3, which were determined as potential regulators of ACER3 expression and known to be activated by cholestasis." (PMID 40025008, 2025). "CER(d18:1/18:1), the substrates of ACER3, exhibited negative correlations with SCSMs in patients with cholestasis, and ACER3 ablation specifically increased CER(d18:1/18:1)." (PMID 40025008, 2025).
Cholestatic liver disease (1 paper, 2025). "Our work lays the groundwork for future therapeutic interventions targeting ACER3 or supplementing CER(d18:1/18:1) to treat cholestatic liver diseases." (PMID 40025008, 2025).
colon cancer (1 paper, 2018). "Ultimately, such modulators could have beneficial effects against the pathogenesis of diseases involving C18:1 ceramide and ACER3 dysregulation including colon cancer and AML." (PMID 30575723, 2018).
cystic fibrosis (1 paper, 2023). Autosomal recessive disorder caused by pathogenic variants in the CFTR gene (cystic fibrosis transmembrane conductance regulator), which encodes a chloride and bicarbonate channel expressed in epithelial cells, and follow the diagnosis criteria. "It was demonstrated that the ASH1 inhibition is linked to Cystic Fibrosis; conversely, the ACER3 inhibition is associated to bacterial infection proliferation." (PMID 36635275, 2023).
dysplasia (1 paper, 2016). A usually neoplastic transformation of the cell, associated with altered architectural tissue patterns. "Taken together, these data highlight an important role for Acer3 in inhibiting persistent colonic and systemic inflammation and inflammation-associated dysplasia." (PMID 26938296, 2016).
Dystonia (1 paper, 2021). An abnormally increased muscular tone that causes fixed abnormal postures. "In the current study, we have identified three novel variants in ACER3 gene in cases with new neurological manifestations including developmental regression, dystonia, and spasticity." (PMID 34281620, 2021).
leukoencephalopathies (1 paper, 2021). "Herein, we present three additional variants as a cause for ACER3-related leukoencephalopathy in 3 cases and discuss their clinical course and serial imaging findings in detail which has resulted in expanding the spectrum of this disorder." (PMID 34281620, 2021). "Mutation in Alkaline Ceramidase 3 (ACER3) gene which encodes alkaline ceramidase enzyme that plays a crucial role in cellular growth and viability has been stated as an uncommon reason for inherited leukoencephalopathies." (PMID 34281620, 2021). "We reported three additional cases of ACER3-related leukoencephalopathy with a younger mean age of onset." (PMID 34281620, 2021). "Here, we report three non-related Iranian families harboring mutations in ACER3 which were discovered by means of WES causing a progressive neurologic disorder in association with leukoencephalopathy." (PMID 34281620, 2021).
lipid metabolism disorders (1 paper, 2023). "Targeted quantitative lipidomics studies confirmed a pathogenic role for variants in genes associated with lipid metabolism disorders, such as PI4KA, PCYT2 and ACER3, in n = 4 cases." (PMID 37679823, 2023).
liver fibrosis (1 paper, 2020). "Fibrosis scores in Acer3−/− livers were significantly lower than those in Acer3+/+ livers, suggesting that Acer3 deficiency inhibits PEWD-induced liver fibrosis." (PMID 31949129, 2020).
pneumonia (1 paper, 2025). An acute, acute and chronic, or chronic inflammation focally or diffusely affecting the lung parenchyma, caused by an infection in one or both of the lungs (by bacteria, viruses, fungi, or mycoplasma.). "In the current study, we identified three critical enzymes (ACER3, UGCG, and GBA) and developed a diagnostic and prognostic predictive model for pneumonia-induced sepsis (PIS), termed the “AUG model”." (PMID 40394027, 2025). "ACER3, UGCG, and GBA were significantly elevated in both pneumonia and PIS groups relative to the healthy controls (P < 0.05)." (PMID 40394027, 2025).
Sepsis (1 paper, 2025). Sepsis is defined as life-threatening organ dysfunction caused by a dysregulated host response to infection. "Future studies should investigate the therapeutic modulation of ACER3, UGCG, and GBA to assess their direct impact on sepsis outcomes." (PMID 40394027, 2025).
infection (13 papers, 2012 to 2023). The state of being infected such as from the introduction of a foreign agent such as serum, vaccine, antigenic substance or organism. "Our qRT-PCR data revealed that sphingolipid metabolic key genes encoding enzymes: Cers2, Gba2, Gla, Asah1, Asah2, Acer2, Acer3, Neu3, Sgpp1, and Sphk1 were robustly upregulated in mRNA levels by the infection of C. sinensis." (PMID 36339341, 2022).
cancer (7 papers, 2016 to 2025). A tumor composed of atypical neoplastic, often pleomorphic cells that invade other tissues. "The results for mRNA expression levels of ASAH-1 and ACER3 in CRC tissue were significantly higher in cancer tissues than in normal paired tissue, respectively (p = 0.0088, 0.0001)." (PMID 37758931, 2023). "ACER3 is associated with the AKT/BAX pathway and activates the S1P phosphorylation of AKT through S1PR2 and PI3K in cancer cells." (PMID 32498325, 2020). "ACER3, alkaline ceramidase 3, induces apoptosis in various endothelial and cancer cells." (PMID 40394027, 2025). "Additionally, ACER3 and C18:1 ceramide dysregulation contribute to the pathogenesis of cancer as an inflammatory disease." (PMID 35565311, 2022). "Additionally, ACER3 expression, which has been shown to regulate cancer pathogenesis, was observed to have an unfavorable overall survival outcome in liver hepatocellular carcinoma and brain lower-grade glioma." (PMID 35565311, 2022). "Similarly to ACER2, ACER3 regulation plays a role in hepatocellular carcinoma, as it inversely correlates with outcomes in these types of cancer patients." (PMID 34071409, 2021). "Given the similar Zn-based active site of ACER3 and the canonical catalytic mechanism we propose, it is likely that hydroxamates, which display strong binding to Zn centers, may be developed as inhibitors of the ACERs for cancer therapy." (PMID 36048828, 2022). "Therefore, the inhibition of ACER3 reduces cell growth and increases cancer cell apoptosis." (PMID 32498325, 2020).
tumor (2 papers, 2016 to 2022). "Interestingly, ACER3 involves in tumorigenesis-related mechanism and modifies tumor progression and radiosensitivity through regulation by lncRNA and miRNA." (PMID 34817752, 2022). "Although Acer3 deficiency did not affect average tumor size, they harbored large tumors more frequently than Acer3+/+ mice." (PMID 26938296, 2016). "We also found that Acer3−/− mice had a greater propensity to develop low-grade dysplasia in the inflamed epithelium and exhibited a higher tumor incidence and greater tumor multiplicity compared with Acer3+/+ mice." (PMID 26938296, 2016).
neurodegenerative disease (1 paper, 2015). A disorder of the central nervous system characterized by gradual and progressive loss of neural tissue and neurologic function. "The Acer3 knockout mouse model can serve as an invaluable tool for elucidating the pathological role for dysregulation of ceramides in neurodegenerative diseases in humans." (PMID 26474409, 2015).
ACER3 also shares sentences with these, for which no sentence is quoted: neurological disorders (2 papers); Ataxia (1); bacterial infection (1); colonic dysplasia (1); Hepatic steatosis (1); inflammation (1); intestinal cancer (1); leukemia (1); liver diseases (1); melanoma (1); myeloma (1); neurodevelopmental disorder (1); peripheral neuropathies (1).